PFKFB3 (6-phosphofructo-2-kinase/fructose-2,6-biphosphatase 3)
Diseases named in the same sentence as PFKFB3 in open-access papers (continued):
Sharing a sentence is not in itself a finding about the gene and the disease.
breast cancer (continued). "Furthermore, inhibition of PFKFB3 by 3PO resulted in accumulation of cells in the G2 phase of the cell cycle in breast cancer cells, but not in iPS cells and fibroblasts." (PMID 26337471, 2015). "Moreover, in specific cellular contexts, such as in breast cancer cells, YAP can enhance glycolytic activity to meet energy demands for cancer cell proliferation via activating the Hedgehog pathway and inducing the expression of glycolysis-promoting factors such as HK2 and PFKFB3." (PMID 37681853, 2023). "Moreover, our findings also suggest that autophagy activation, not inhibition, could function to alleviate aberrant Pfkfb3 expression and maintain disseminated BCSCs in a state of perpetual dormancy, thus prolonging the overall survival of breast cancer patients." (PMID 31413316, 2019). "Similarly, in MCF7 breast cancer cells SLC2A1, HK2, and PFKFB3 but not ENO1 or LDHA were strongly induced by hypoxia." (PMID 23866118, 2013).
Sepsis (29 papers, 2019 to 2026). Sepsis is defined as life-threatening organ dysfunction caused by a dysregulated host response to infection. "Elevated PFKFB3 is closely associated with excessive inflammatory responses and high mortality in sepsis." (PMID 40618046, 2025). "A growing body of evidence suggests that an increase in PFKFB3-driven glycolysis in immune cells is intimately linked with the excessive inflammatory response observed in sepsis." (PMID 38705396, 2024). "In the context of sepsis, there is a transition of PFK2 from the less active L-type, which is encoded by the fructose-2,6-bisphosphatase 1 (PFKFB1) gene, to the more potent U-type, encoded by the fructose-2,6-bisphosphatase 3 (PFKFB3) gene." (PMID 39712019, 2024). "PFKFB3 is found to be overexpressed in various cells implicated in sepsis, including macrophages, neutrophils, endothelial cells, and lung fibroblasts." (PMID 38705396, 2024). "It is evident that upregulation of PFKFB3 is closely associated with excessive inflammation and high mortality in sepsis." (PMID 39712019, 2024). "Recent studies have shown that PFKFB3 expression is markedly enhanced in several animal models of disease, such as acute kidney injury, acute lung injury, and sepsis, and the underlying mechanisms have been investigated." (PMID 37509108, 2023). "Alterations in the levels of PFKFB3 have been reported in different sepsis-associated cells, such as macrophages, neutrophils, endothelial cells (ECs) and lung fibroblasts." (PMID 37199341, 2023). "A recent study found that targeting PFKFB3 to block glycolysis alleviates acute lung injury associated with sepsis by inhibiting inflammation, ROS production, and apoptosis of alveolar epithelial cells." (PMID 36589684, 2022). "3-(3-Pyridinyl)-1-(4-pyridinyl)-2-propen-1-one (3PO), the specific inhibitor of PFKFB3, and Gsdmd gene knockout significantly inhibited the inflammatory response and cell death caused by sepsis, thus alleviating intestinal damage and barrier dysfunction." (PMID 36589684, 2022). "In the current study, we identified a causative role of macrophage Pfkfb3-dependent glycolysis in LPS-induced sepsis through regulation of macrophage inflammation." (PMID 34660743, 2021). "To determine the contribution of Pfkfb3-mediated glycolysis in macrophages to LPS-induced sepsis, we generated myeloid-specific Pfkfb3 deficient mice (Pfkfb3ΔMφ) and control mice (Pfkfb3WT) by intercrossing Pfkfb3flox/flox mice with Lysm-Cre mice." (PMID 34660743, 2021). "The protein encoded by PFKFB3 is an important enzyme in glycolysis, and the protein contributes to cell apoptosis, enhancement of ROS, and the development of sepsis." (PMID 31093495, 2019). "Moreover, mice with a myeloid-specific PFKFB3 deficiency exhibit increased survival in a murine sepsis model, as well as increased lymphangiogenesis following myocardial infarction." (PMID 41235226, 2025). "In addition, sepsis caused by infection from Escherichia coli not only increases the expression of PFKFB3 but also enhances the levels of Ser461-phosphorylated PFKFB3 in bone marrow-derived macrophage and further promotes inflammation processes." (PMID 40307939, 2025). "Therefore, in a mouse model of LPS-induced sepsis, endothelium-specific PFKFB3 deficiency or 3-(3-pyridyl)-1-(4-pyridyl) -2-propenyl-1-one (3PO) inhibition of PFKFB3 significantly reduced pulmonary edema and improved survival." (PMID 39318551, 2024). "Furthermore, the pharmacological inhibition of glycolysis by targeting PFKFB3 has been associated with a decrease in mortality, positioning PFKFB3 as a promising therapeutic target for mitigating excessive inflammation in sepsis." (PMID 38705396, 2024). "Furthermore, increased PFKFB3 is associated with an excessive inflammatory response in sepsis." (PMID 37199341, 2023). "The degradation of Pfkfb3 mRNA leads to impaired glycolysis and suppresses immune responses in AMs after sepsis." (PMID 41178622, 2026).
Sepsis (continued). "In line with this, treatment with the PFKFB3 inhibitor 3PO alleviated inflammation and reduced mortality in murine sepsis models." (PMID 41235226, 2025). "Enhancement of PFKFB3 transcription and translation facilitates the production of neutrophil inflammatory factors during the acute phase of sepsis." (PMID 39969221, 2025). "Our study highlights the potential of key genes, such as HP and PFKFB3, to uncover novel regulatory pathways and identify key molecular targets for improving sepsis diagnosis, treatment and prognosis." (PMID 38227599, 2024). "In this study, we reanalyzed publicly available RNA-seq datasets and identified miR-106a-5p as the most efficient human miRNA for abrogating PFKFB3 expression and inhibiting macrophage pyroptosis and inflammatory response in sepsis." (PMID 38705396, 2024). "During sepsis, PFKFB3 expression is rapidly upregulated, leading to its phosphorylation and subsequent activation (at approximately 6 h post-LPS stimulation)." (PMID 39356055, 2024). "Several studies have demonstrated that the transcription factors hypoxia-inducible factor 1α and zinc fingers and homeoboxes 2 can transcriptionally upregulate Pfkfb3 in the context of sepsis." (PMID 38705396, 2024). "Long noncoding RNA GSEC has been shown to bolster neutrophil inflammatory activation by sustaining PFKFB3-involved glycolytic metabolism in the context of sepsis." (PMID 39712019, 2024). "PFKFB3, a key glycolytic enzyme, has been shown to promote the overactivation of macrophages and the development of sepsis." (PMID 38705396, 2024). "Comparing these 13 downregulated miRNAs with the miRNAs identified using the TARGETSCAN database; we found that miR-106a-5p was the only miRNA with the potential to target PFKFB3 in sepsis." (PMID 38705396, 2024). "Through multiple meta-analyses, we observed a downregulation of miR-106a-5p expression and an upregulation of PFKFB3 expression in clinical sepsis samples." (PMID 38705396, 2024). "To assess the therapeutic potential of miR-106a-5p in vivo and its reliance on Pfkfb3 inhibition, we established an LPS-induced sepsis model in both Pfkfb3+/+/LysMcre/+ mice (serving as WT controls) and Pfkfb3flox/flox/LysMcre/+ mice." (PMID 38705396, 2024). "In the cell experiments, it was found increased expression of HP and PFKFB3 in sepsis, and there existed a positive relation between them." (PMID 38227599, 2024). "In the present study, we observed the upregulation of Pfkfb3 and downregulation of miR-106a-5p in blood monocytes from patients with early sepsis and from an LPS-induced sepsis mouse model for the first time." (PMID 38705396, 2024). "Transcription factor Zhx2 enhances PFKFB3 transcription by binding to the PFKFB3 promoter, thereby contributing to macrophage metabolic reprogramming and accelerating sepsis progression." (PMID 39712019, 2024). "In our investigation, we discovered that the expression of PFKFB3 is significantly elevated in the blood mononuclear cells of patients with sepsis." (PMID 38705396, 2024). "Despite its importance, the development of strategies to target PFKFB3 in the context of sepsis remains challenging." (PMID 38705396, 2024). "Through in vitro experiments, we demonstrate that HP enhances PFKFB3 transcription and translation, thereby promoting the production of neutrophil inflammatory cytokines in sepsis and playing a crucial role in promoting neutrophil glycolysis." (PMID 38227599, 2024). "Given the pro-inflammatory effect of HP, our research reveals that HP-regulated PFKFB3-mediated glycolytic reprogramming is a possible sepsis treatment target." (PMID 38227599, 2024). "The expression of PFKFB3 is significantly increased in sepsis-related cells such as macrophages, neutrophils, endothelial cells, and pulmonary fibroblasts, promoting the activation of aerobic glycolysis and leading to acute lung injury." (PMID 39712019, 2024).
Sepsis (continued). "Inhibition of PFKFB3 can improve sepsis induced by LPS or cecal ligation, suggesting its potential as a treatment target." (PMID 38705396, 2024). "The inhibition of PFKFB3 is a promising strategy for mitigating inflammatory damage, improving sepsis prognosis, and suppressing fibrosis progression." (PMID 39356055, 2024). "Targeting dysregulated EC metabolism has recently (re)gained increased interest as a therapeutic strategy for sepsis, and it is worth noting that several studies have shown beneficial effects of PFKFB3 inhibition in acute sepsis-induced lung injury models." (PMID 38020105, 2023). "In the present review, we summarize the role of PFKFB3 in sepsis based on the latest studies in the field of PFKFB3 gene and protein." (PMID 37199341, 2023). "A recent study showed that hypoxia, a common pathophysiological change in sepsis, induces enhanced PFKFB3-involved glycolysis in macrophages, and the mechanism involved the PI3K/Akt/mTOR and HIF-1α signaling cascades." (PMID 37199341, 2023). "Inhibition of PFKFB3 has additionally shown great potential in reducing inflammatory damage and improving the prognosis of sepsis." (PMID 37199341, 2023). "Recent studies have revealed that sepsis accelerates the rate of PFKFB3-driven glycolysis in different cells, including macrophages, neutrophils, endothelial cells and lung fibroblasts." (PMID 37199341, 2023). "All of these results indicated that PFKFB3-driven macrophage glycolysis is a potential therapeutic target for sepsis." (PMID 37199341, 2023). "Of these cells types, most published studies are on the role of PFKFB3-driven glycolysis in the polarization of macrophages in sepsis." (PMID 37199341, 2023). "In the same year, Pei and colleagues found that cynaroside, a flavonoid compound, mitigates sepsis-induced liver injury by inhibiting PFKFB3-driven glycolytic metabolism and then preventing macrophage polarization into the M1 phenotype." (PMID 37199341, 2023). "In this section, we will review in detail the studies related to PFKFB3-driven glycolysis and sepsis-induced damage to ECs and lung fibroblasts." (PMID 37199341, 2023). "In recent years, several published studies have indicated that PFKFB3-driven glycolysis reprogramming plays an important role in sepsis-induced EC and lung fibroblast damage." (PMID 37199341, 2023). "In sepsis, PFKFB3 is rapidly (approximately 6 h after LPS stimulation) increased and phosphorylated, which contributes to the rapidly increased glycolytic flux and subsequent inflammatory injury." (PMID 37199341, 2023). "To further investigate the role of PFKFB3 in sepsis-induced intestinal dysfunction, we established CLP mice and intervened with the PFKFB3 inhibitor 3PO." (PMID 36589684, 2022). "The results showed that the expression of 6-phosphofructo-2-kinase/fructose-2,6-biphosphatase 3 (PFKFB3) in the small intestines was significantly upregulated in sepsis." (PMID 36589684, 2022). "This study is aimed at investigating the protective effect and mechanism of PFKFB3 inhibition on intestinal barrier dysfunction in sepsis mice." (PMID 36589684, 2022). "In the present study, we explored the role and mechanism of PFKFB3 in sepsis barrier dysfunction using PFKFB3 small molecule inhibitor 3PO and Gsdmd−/− mice." (PMID 36589684, 2022). "In agreement with this study, our results showed that the expression level of GSEC was significantly increased in sepsis-induced neutrophils and it influenced glycolysis in dHL-60 cells by directly enhancing PFKFB3 mRNA transcription and translation." (PMID 34907156, 2021). "In agreement with this study on leukocytes, our results showed that during the acute phase of sepsis, the expression level of PFKFB3 mRNA was upregulated in primary human neutrophils." (PMID 34907156, 2021). "Deletion of myeloid Pfkfb3 reduces LPS-induced sepsis and inflammatory responses by decreasing lung infiltration of macrophages and neutrophils and improving lung edema, cardiac dysfunction and hypotension." (PMID 34660743, 2021).
Sepsis (continued). "In summary, our study reveals the critical role of Pfkfb3 in LPS-induced sepsis via reprogramming macrophage metabolism and regulating proinflammatory gene expression." (PMID 34660743, 2021). "Our findings here expand our understanding of glycolytic regulation of sepsis and indicate PFKFB3 as an attractive potential therapeutic target for the prevention and treatment of sepsis." (PMID 34660743, 2021). "Myeloid Pfkfb3 knockout-decreased macrophage inflammatory response protects mice from LPS-induced sepsis." (PMID 34660743, 2021). "The adenosine monophosphate-activated protein kinase pathway, which is extensively involved in cellular energy homeostasis, was also upregulated and associated with three co-expressed mRNAs (CAB39, PFKFB3, and PRKAA1) in sepsis." (PMID 34907156, 2021). "In summary, our study uncovers a mechanism by which GSEC lncRNA promotes neutrophil inflammatory activation in sepsis by supporting glycolytic metabolism with PFKFB3." (PMID 34907156, 2021). "In conclusion, our study showed that GSEC plays a pivotal role in promoting glycolysis in neutrophils by enhancing PFKFB3 transcription and translation, facilitating neutrophil inflammatory factors production during the acute phase of sepsis." (PMID 34907156, 2021). "All of these results demonstrate that the glycolytic enzyme PFKFB3 plays a critical role in sepsis-induced neutrophil activation." (PMID 34907156, 2021). "Furthermore, a significant increase has been observed in the expression of PFKFB3 in LPS-challenged and sepsis neutrophils compared with healthy controls." (PMID 39969221, 2025). "Endothelial cells (ECs) in sepsis also undergo a shift from oxidative phosphorylation (OxPhos) to glycolysis, mediated by enzyme 6-phosphofructo-2-kinase/fructose-2,6-bisphosphatase isoform 3 (PFKFB3), a key glycolytic enzyme." (PMID 40735670, 2025). "In addition, the M1 polarization and glycolysis of alveolar macrophage was induced by FoxO3-mediated activation of PFKFB3 in sepsis-related acute lung injury." (PMID 38725041, 2024). "Furthermore, treatment with agomir-miR-106a-5p conferred a protective effect in an LPS mouse model of sepsis, but this effect was attenuated in myeloid-specific Pfkfb3 KO mice." (PMID 38705396, 2024). "Additionally, downregulation of PFKFB3 expression can inhibit macrophage pyroptosis and inflammation during sepsis, thus suppressing sepsis development." (PMID 39712019, 2024). "We then evaluated the therapeutic effect of miR-106a-5p against sepsis and found that treatment with agomir-miR-106a-5p, by reducing Pfkfb3 levels, was able to alleviate macrophage pyroptosis, inflammatory response, and lung injury in a lipopolysaccharide (LPS)-induced sepsis mouse model." (PMID 38705396, 2024). "However, upon LPS stimulation, PFKFB3 levels markedly increase in cells pertinent to sepsis, including macrophages, neutrophils, endothelial cells, and lung fibroblasts." (PMID 39712019, 2024). "Moreover, PFKFB3 intensifies the formation of neutrophil extracellular traps (NETs), thereby exacerbating sepsis-induced acute lung injury." (PMID 39712019, 2024). "Therefore, targeting neutrophil PFKFB3-driven glycolysis is a potential therapeutic strategy to modulate neutrophil functions in sepsis." (PMID 37199341, 2023). "Targeting PFKFB3-driven EC glycolysis is an efficient therapeutic strategy for sepsis." (PMID 37199341, 2023). "In conclusion, sepsis accelerates PFKFB3-driven glycolysis in macrophages." (PMID 37199341, 2023). "In addition, the role of PFKFB3-involved glycolysis in sepsis-induced EC dysfunction has gradually emerged in recent years." (PMID 37199341, 2023). "Interestingly, inhibition of PFKFB3 alone or in combination has also shown great potential in the treatment of sepsis." (PMID 37199341, 2023). "Therefore, we will review in detail the studies related to PFKFB3-driven glycolysis in macrophage polarization and neutrophil activation in sepsis." (PMID 37199341, 2023).